MET (MET proto-oncogene, receptor tyrosine kinase)
Diseases named in the same sentence as MET in open-access papers (continued):
Sharing a sentence is not in itself a finding about the gene and the disease.
lung cancer (continued). "Here, we reported that miR-329 was indeed suppressed in primary lung cancers tissues compared with the matching normal lung tissues, and found 3′-UTR of the human MET mRNA is really a target of miR-329." (PMID 26909600, 2016). "In summary, AUY922 exerts effective control over malignant phenotypes that are driven by MET and AXL, including drug resistance, in lung cancer." (PMID 25780909, 2015). "Here, we reported that miR-206 is indeed suppressed in primary lung cancers compared with the matching normal tissues, and found 3′-UTR of the human MET and BCL2 mRNA are really targets of miR-206." (PMID 26325180, 2015). "Silence of MET and BCL2 expression inhibits lung cancer cell (A549 and SK-MES-1) growth, migration, invasion and apoptosis." (PMID 26325180, 2015). "Our study findings thus show that AUY922 is a promising therapeutic option for MET- and AXL-mediated resistance to EGFR-TKI in lung cancer." (PMID 25780909, 2015). "Amplification of c-Met (MET) has been detected in lung cancer cells developing resistance to Gefitinib or Erlotinib." (PMID 25993617, 2015). "Crizotinib activity has been reported in MET-amplified tumors, with ongoing studies in EGFR TKI-resistant lung cancer of MET and HGF-targeted agents, such as ficlatuzumab (anti-HGF monoclonal antibody, NCT02034981)." (PMID 25505733, 2014). "Whereas, in the cancers of esophagus, oral cavity, lung, and head and neck, miR-27a is downregulated, and miR-27a directly targets MET and EGFR and suppresses their expression in lung cancer." (PMID 25166914, 2014). "Lung cancer cells were treated with the single EGFR TKIs gefitinib, erlotinib, or afatinib, and in combination with c-MET inhibitor su11274." (PMID 23527257, 2013). "We previously reported that HGF activates the MET/GAB1 pathway and increases VEGF production by EGFR mutant lung cancer cells." (PMID 23690929, 2013). "Actually, MET tyrosine phosphorylation occurs in A549 lung carcinoma cells within 10 min after HGF addition, while NK4 inhibits the HGF-mediated MET activation." (PMID 23296269, 2013). "In lung cancer it has been shown that, due to its cross reactivity/compensation effect with EGFR, HGFR/c-MET gene amplification can confer resistance to EGFR-targeting drugs." (PMID 22606042, 2012). "To examine the roles of MET, EGFR, HER2, HER3, and RET in lung cancer cells with MET amplification, we first investigated the effects of PHA-665752, gefitinib, lapatinib, and vandetanib on cell proliferation and survival." (PMID 21847121, 2011). "As MET and EGFR often co-express in lung cancer cells, we asked if there is signalling cross-activation between MET and EGFR pathways." (PMID 19238632, 2008). "Immunoprecipitation studies of the MET and EGFR under single- or dual-ligand stimulation confirmed the presence of receptor cross-activation between MET and EGFR in these lung cancer cell lines." (PMID 19238632, 2008). "The erlotinib-resistant lung cancer cell line H1975, which expresses L858R/T790M-EGFR in-cis, was used to test for the effect of MET inhibition using the small molecule inhibitor SU11274." (PMID 19238632, 2008). "The constitutive activation of HER3 signalling in TKI-resistant lung cancers can also be mediated through the amplification of MET, recently identified in certain TKI-resistant subclones of lung cancer cells." (PMID 17667926, 2007). "Targets in lung cancer mainly include HER2, HER3, TROP2, MET, CEACAM5, B7-H3 etc." (PMID 41020004, 2025). "In lung cancer, where actionable alterations such as EGFR, ALK, ROS1, and MET have direct therapeutic implications, optimizing patient selection for NGS testing could further enhance cost-efficiency." (PMID 41301039, 2025). "The management of advanced non–small cell lung cancer (NSCLC) has been revolutionized by the development of targeted therapies for tumors harboring driver alterations in EGFR, anaplastic lymphoma kinase, MET, and other genes." (PMID 40310449, 2025).
lung cancer (continued). "Known lung cancer genes (EGFR, KRAS G12C, ALK, MET, RET) were found in 33 patients; 11 had genes relevant to both lung and other cancers (ERBB2, BRAF V600, NTRK), and 37 had genes typically linked to other malignancies (NF1, PIK3CA, PALB2, FGFR2B, FBX7, RAD51)." (PMID 40244261, 2025). "Here, we present a 10XGenomics scRNA-seq experiment, providing a controlled heterogeneous environment using lung cancer cell lines characterised by the expression of seven different driver genes (EGFR, ALK, MET, ERBB2, KRAS, BRAF, ROS1), leading to partially overlapping functional pathways." (PMID 38307867, 2024). "Additionally, our findings follow previous results showing that NPS-1034 plays a crucial regulatory role as an inhibitor in both the MET and AXL pathways in solid tumors, such as lung cancer and gastric cancer." (PMID 39451232, 2024). "One of the primary downstream effects of c-MET activation is the MAPK/ERK (Ras, Ras/Raf/MEK/ERK) signaling cascade, and MEK (Mitogen-activated protein kinase kinase) inhibitors have demonstrated therapeutic value in RAS-mutant melanoma and lung cancer." (PMID 38473413, 2024). "The interaction between lung cancer cells and cancer-associated fibroblasts (CAFs) occurs via the HGF/c-Met signaling pathway, whereby lung cancer cells stimulate CAFs to release HGF, leading to the activation of c-MET and subsequent promotion of lung cancer cell proliferation and survival." (PMID 39201787, 2024). "In the GEO database, the expression levels of MET, ETS-1, and USP9X in osimertinib-resistant lung cancer cells, as observed in the datasets GSE202859 and GSE236654, were significantly higher than those found in osimertinib-sensitive lung cancer cells." (PMID 39468027, 2024). "MET inhibitors have shown significant benefit for treatment in MET amplified lung cancers (tier-II), however, data for OC is currently still lacking." (PMID 38519644, 2024). "It was reported that engaging the overexpressed MET in lung cancers with a biparatopic ADC, METxMET‐M114, provided more benefits than merely blocking the MET function and had the potential to overcome acquired resistance to MET‐selective tyrosine kinase inhibitors." (PMID 39545074, 2024). "Likewise, in GSE253742, MET, ETS-1, and USP9X expression levels in lung cancer tissues after osimertinib treatment were elevated compared to untreated lung cancer tissues, supporting our research findings." (PMID 39468027, 2024). "Furthermore, PIM1 has been demonstrated to induce resistance to MET inhibitors in cell lines with MET gene amplification, such as EBC-1 (a lung cancer cell line) and MKN45 (a gastric cancer cell line)." (PMID 37381723, 2023). "In all, 8398 (98%) were adults and 195 (2%) were children; 7865 patients (92%) were treated for lung cancer, of whom 7270 (92%) had an ALK rearrangement, 290 (4%) had an ROS1 rearrangement and 305 (4%) had another molecular abnormality, such as in RET, MET, or NTRK." (PMID 37894307, 2023). "Preclinical cases suggest that EGFR tyrosine kinase inhibitors (TKIs) plus MET TKIs are a potential therapy for non-classical EGFR mutant lung cancers with MET amplification acquired resistance." (PMID 36910616, 2023). "Thus, we conducted a correlation study between FGF11 and EGFR (19DEL, L858R), EGFR (Exon 20ins), KRAS (G12C), ALK, ROS1, BRAF, NTRK1/2/3, MET, and RET, which are all recommended by the NCCN guidelines for the diagnosis of nonsmall cell lung cancer." (PMID 37250453, 2023). "We also demonstrate that this phosphorylation is decreased following pharmacologic inhibition of DNA-PK in the gastric cancer cell line GTL-16 as well as the lung cancer cell line EBC-1, two MET receptor-addicted cancer cell lines characterized by an amplified MET gene copy number." (PMID 37188738, 2023).
lung cancer (continued). "Admittedly, the current study is not without limitations for confirming the role of MET fusions in the development of lung cancer resistance to EGFR/ALK-TKIs, and further exploration of these rare actionable genomic alterations is needed." (PMID 36829199, 2023). "None of the 1293 lung carcinomas with driver alterations in EGFR/ALK/ROS1/RET/MET oncogenes had NTRK 5′/3′-end expression imbalances." (PMID 37762506, 2023). "A study using H1975 lung cancer cells resistant to afatinib showed that treatment with HDAC inhibitors sodium valproate or AR42 decreased the expression of several members of the tyrosine kinase receptor family: ERBB1, ERBB2, ERBB3 and ERBB4, and c-MET." (PMID 36263432, 2022). "The crosstalk of the MET and KRAS pathways could confer resistance to lung cancer-targeted therapies." (PMID 36230855, 2022). "Since patients who developed EGFR mutant lung adenocarcinomas with acquired resistance to EGFR inhibitor drugs (gefitinib or erlotinib) exhibit increased copy numbers of MET, c-Met-HGF inhibitors are used for lung cancer treatment alone or in combination with other drugs." (PMID 35986321, 2022). "And dual inhibition of MET and EGFR might be a therapeutic strategy for EGFR-driven drug resistance METex14 lung cancer." (PMID 36338758, 2022). "While MACC1 exerts its prometastatic effects by activating MET in various human cancers, including colon, gastric, liver and lung cancer, its prometastatic effects in PC are independent of MET activation according to our study." (PMID 36333284, 2022). "Interestingly, MET exon 14 skipping alterations occur in 3–4% of NSLCL, and MET inhibitors are active in patients with advanced MET exon 14-altered lung cancers." (PMID 35407463, 2022). "In addition, Crizotinib, a multikinase inhibitor used in lung cancer patients with ALK or ROS1 translocations, showed a beneficial effect in patients with MET alterations." (PMID 34733418, 2021). "For example, the discovery of MET amplification in a subset of resistant EGFR-mutant lung cancers has now led to promising activity of combination EGFR and MET TKIs in EGFR-mutant lung cancer patients with acquired resistance due to MET amplification." (PMID 34071428, 2021). "Furthermore, suppression of MIR22HG significantly accelerated lung cancer cell proliferation via YBX1, MET, and p21 in lung cancer." (PMID 34187303, 2021). "Meanwhile, the level of m6A decreased in lung cancer cells that METTL3 was knocked down, suggesting that METTL3 may affect the expression of MET through the m6A pathway." (PMID 33491264, 2021). "We further analyzed mRNA expression of 67 genes in 5 ALK-positive lung cancer samples and the corresponding pericarcinous (normal) tissues by NanoString assay, and found increased mRNA of ALK, ROS1, MET, SPP1 and PI3K signaling pathway in ALK-positive lung cancer." (PMID 34234236, 2021). "RT-PCR and qPCR showed that the transcript level of MET was not influenced by knockdown of SIPA1 in A549 lung cancer cells." (PMID 33917539, 2021). "In vitro studies on lung cancer cells showed that decrease in phosphorylation level of extracellular signal-regulated kinase (ERK) 1/2 and Akt mediated by FGFR inhibition with AZD4547 or BAY1163877 was hampered by MET activation." (PMID 33898310, 2021). "In lung cancer cells, a signaling network exists between the same RTK family: EGFR, MET, and ERBB3." (PMID 32070026, 2020). "The difference of recurrence of EGFR/ERBB2/MET is probably due to the different stage of tissues, as the majority data of MSKCC-IMPACT is from late-stage biopsy tissues; while TCGA NSCLC cohort, from early-stage lung cancer primary tumor tissues." (PMID 31739500, 2019). "Taken together, the results suggest a complex interaction between MET and EGFR in NSCLC in the presence of EGFR TKIs and provide unique insight into potential resistance mechanisms and management strategies in EGFR/METex14-altered lung cancers." (PMID 31157314, 2019).
lung cancer (continued). "Lung cancer organoids respond to drugs based on their genomic alterations: a BRCA2-mutant organoid to olaparib, an EGFR-mutant organoid to erlotinib, and an EGFR-mutant/MET-amplified organoid to crizotinib." (PMID 31488816, 2019). "Although many therapies targeting c-MET are part of ongoing clinical trials, there is no general consensus on how c-MET status should be tested in lung cancer tissues or what the relationship is between the results obtained by FISH and IHC." (PMID 29416799, 2018). "Moreover, the levels of HGF are increased in lung cancer tissue compared to normal lung mucosa, suggesting that inhibition of pro-HGF activation is a valid approach to inhibit HGF/MET signaling." (PMID 28968967, 2017). "MET-amplified lung cancer cells do not respond to EGFR inhibitors, but are highly sensitive to MET inhibition." (PMID 28968967, 2017). "The tyrosine kinase c-Met, also called MET and hepatocyte growth factor receptor (HGFR), is a key regulator of organ development and cancer progression and has been studied in many cancer types such as lung cancer, gastric cancer, prostate cancer and so on." (PMID 28915628, 2017). "However, some lung cancer cells fail to respond to combined treatment with EGFR and MET inhibitors or develop resistance to dual EGFR/MET inhibition." (PMID 28420162, 2017). "In this study, we found that MET/EGFR and their downstream signaling ERK1/2 and AKT may be the targets of FAM83H-AS1 in lung cancer, indicating that FAM83H-AS1 may be a potential therapeutic target." (PMID 28198463, 2017). "Although both MET gene amplification and HGF treatment has been shown to induce gefitinib resistance in lung cancers with EGFR mutations, ErbB3 transactivation is involved only in MET amplification but not in HGF-induced resistance." (PMID 26919104, 2016). "Apart from MET, it has been recently reported that the VEGFR receptor family could have a prognostic potential in lung cancer." (PMID 27528792, 2016). "This may be the result of heterogeneity or variation in p-MET or the activation of compensatory pathways (e.g., EGFR, KRAS) in lung cancer." (PMID 27013592, 2016). "The clinicopathologic characteristics of lung cancer patients with MET exon 14 skipping have not yet been described." (PMID 27223439, 2016). "MET exon 14 skipping was not reckoned as a driver in lung cancer until the high-throughput sequencing revealed that this mutant kinase was mutually exclusive with known driver events." (PMID 27223439, 2016). "Next, we explored whether inhibition of MET, the receptor of HGF, could restore the sensitivity to gefitinib in lung cancer cells with wild-type EGFR that were pretreated with HGF." (PMID 26919104, 2016). "Therefore, to explore the molecular mechanism by which HGF reduces sensitivity to gefitinib in lung cancer harboring wild-type EGFR, we examined the phosphorylation status of MET, EGFR, ErbB3, and the downstream signaling pathways by western blotting." (PMID 26919104, 2016). "We next examined the potential tumorigenicity of MET and BCL2 in lung cancer." (PMID 26325180, 2015). "Although these studies have demonstrated the capability of HSP90 inhibitors to down-regulate MET, they did not evaluate MET-mediated resistance to EGFR-TKI in lung cancer." (PMID 25780909, 2015). "Thus, combined use of MET tyrosine kinase inhibitor (TKI) and EGF TKI has been suggested to be a valid novel combination to overcome TGF TKI acquired resistance in lung cancer." (PMID 26310485, 2015). "Because various oncoproteins depend on HSP90 for maturation and stability, we investigated the effects of AUY922, a newly developed non-geldanamycin class HSP90 inhibitor, in lung cancer cells with MET- and AXL-mediated resistance." (PMID 25780909, 2015).
lung cancer (continued). "Heat shock protein 90 is a chaperone protein that assists posttranslational folding of several proteins to stabilize and protect them from cellular stresses like heat or hypoxia, including critical proteins in lung cancer such as EGFR, HER2, MET, ALK, and others." (PMID 25505733, 2014). "Targeting MET protein-expressing lung cancer has not been successful to date, with negative phase III trials of onartuzumab (anti-MET monoclonal antibody), and TKIs including tivantinib." (PMID 25505733, 2014). "In a study using 32 lung cancer tissues, all tumor samples expressed MET with no significant MET staining in corresponding normal lung tissues, and 61% (14 of 23) of NSCLC showed strong MET expression examined by IHC." (PMID 27234388, 2013). "MET, the receptor tyrosine kinase for hepatocyte growth factor (HGF) has been shown to drive tumorigenesis when overactivated in a number of cancers, including lung cancer." (PMID 23300999, 2013). "This type of analysis predicts how the lipid metabolic pathway may functionally interact with EGFR, MET, and other biological processes in lung cancer cells, and offers an insight into the roles of EGFR and MET inhibition in lung cancer therapeutics." (PMID 22211244, 2012). "Continuous administration of gefitinib or erlotinib in lung cancer patients with MET amplification did not interrupt tumor progression, regardless of EGFR status." (PMID 22489192, 2012). "Together, these results suggested that MET, EGFR, HER2, and HER3 activate AKT and ERK signalling pathways and promote cell proliferation and survival in lung cancer cells with MET amplification, whereas MET, HER2, and RET activate the STAT3 signalling pathway and promote cell migration." (PMID 21847121, 2011). "We found that the EGFR–TKI gefitinib did not inhibit EGFR phosphorylation in lung cancer cells with MET amplification." (PMID 21847121, 2011). "EGFR, HER2, and HER3 appear to activate signalling by forming a complex with MET in a manner dependent on MET kinase activity rather than on their own kinase activity in lung cancer cells with MET amplification." (PMID 21847121, 2011). "Furthermore, a recent study has revealed Gab1 not only as a convergence point between c-MET and EGFR pathways, but also suggests that Gab1 cooperates with MET amplification in lung cancer cells, which have become resistant towards the EGFR inhibitor gefitinib." (PMID 19737390, 2009). "Taken together, these data provide support that cooperative enhanced inhibition using dual TKIs against MET and EGFR pathways may be an effective treatment strategy to inhibit lung cancer with intrinsic or acquired T790M-EGFR-mediated TKI resistance." (PMID 19238632, 2008). "We first examined the expression pattern of MET and EGFR in lung cancer cell lines." (PMID 19238632, 2008). "The TMB was significantly higher in the lung cancer cohort than in the brain tumor cohort across the overall populations and within the following subgroups: all MET CNV, CNV2‐5, CNV 5–10, CNV ≥ 10 and MET segmental amplification (p < 0.001 for all; Wilcoxon test)." (PMID 41521799, 2026). "LINC00857 is upregulated in lung cancer cells by a mechanism that involves LINC00857 binding to YBX1, preventing its proteasomal degradation, increasing its nuclear translocation, and promoting MET expression to regulate biological processes such as cell proliferation." (PMID 41507135, 2026). "Secondary mutations in the EGFR driver gene are a primary cause of resistance to EGFR-TKIs 2, 3; in addition, other mutations including BRAF, PIK3CA, HER2 or c-MET amplifications, which were independent of EGFR pathway, account for 5-20% in EGFR-TKIs resistant lung cancer." (PMID 39744423, 2025). "For patients with lung cancer, we assessed the presence of EGFR mutations and found no clear association with anti-MET responses, as only 2 patients in the cohort had EGFR mutations, one of whom exhibited a response to MET." (PMID 40401526, 2025).